PLK1 (polo like kinase 1)
Diseases named in the same sentence as PLK1 in open-access papers (continued):
Sharing a sentence is not in itself a finding about the gene and the disease.
hepatocellular carcinoma (50 papers, 2010 to 2026). A malignant tumor that arises from hepatocytes. "Aberrant promoter methylation of PLK1-4 have been implicated in hepatocellular carcinoma, while PLK2 promoter hypermethylation has been detected in hematologic malignancies such as acute myeloid leukemia and B-cell lymphoma, as well as in ovarian cancers." (PMID 24498222, 2014). "As expected, the knockdown of Plk1 alleviated severe liver carcinoma caused by Setd3." (PMID 35912180, 2022). "Tumor CDC25A expression was strongly associated with metastatic diseases in hepatocellular carcinoma, and PLK1 could be an upstream regulator of CDC25A." (PMID 29246203, 2017). "There are studies have shown that the higher frequency of G allele in Asian population can make PLK1 more susceptible to the inhibition of human microrna: hsa-miR-100-5p, which is more conducive to the prognosis of hepatocellular carcinoma (HCC)." (PMID 40612941, 2025). "PLK1 inhibitors have been shown in several studies to achieve promising results in the treatment of hepatocellular carcinoma." (PMID 40486867, 2025). "In hepatocellular carcinoma, PLK1 interacts with PTEN and interferes with its nuclear translocation, leading to the inhibition of natural killer (NK) cell and T cell function by enhancing aerobic glycolysis and promoting M2 macrophage polarization." (PMID 40612941, 2025). "PLK1 gene was highly expressed in various cancers, including bladder uroepithelial carcinoma, hepatocellular carcinoma, LA as well as gastric adenocarcinoma." (PMID 37744268, 2023). "Correlation analysis indicated that upregulated SETD3 was positively correlated with higher levels of PLK1 in hepatocellular carcinoma samples (R = 0.4847, p = 0.021)." (PMID 35912180, 2022). "In contrast, MARylation of polo-like kinase 1 (PLK1) inhibits the kinase activity and oncogenic function of PLK1 in hepatocellular carcinoma (HCC)." (PMID 35652091, 2022). "In human tumor cell lines, the expression level of PLK1 mRNA was the most abundant in human hepatocellular carcinomas cell lines (Hep G2), followed by human leukemia cell lines (HAP1)." (PMID 36618405, 2022). "Still, ARTD10 ADP-ribosylates PLK1, significantly inhibiting its kinase activity and oncogenic function in hepatocellular carcinoma (HCC)." (PMID 33440786, 2021). "Inhibition of PLK1 was also reported to induce anticancer effect in hepatocellular carcinoma and retinoblastoma cell lines." (PMID 30042885, 2018). "In hepatoma cells, the target gene PLK1 of lncRNAP26302 was overexpressed, inhibiting the expression of Myt1 and reducing the inhibitory effect of Myt1 on CycA/CDK1." (PMID 30364632, 2018). "Here we illustrated the clinicopathological significance of PLK1 expression in hepatocellular carcinoma (HCC) in more detail." (PMID 25019081, 2014). "Therefore, our data suggest that elevated SETD3 induces hepatocellular carcinoma by enhancing PLK1 expression." (PMID 35912180, 2022). "In one study, dendrimers conjugated with epidermal growth factor (EGF), human serum albumin (HSA) and nimotuzumab antibody (h-R3) were used to deliver siRNA against polo-like kinase-1 (PLK1) to the EGFR-overexpressing hepatocellular carcinoma cell line (HepG2) and tumor-bearing BALB/c nude mice." (PMID 33805602, 2021). "In hepatocellular carcinoma (HCC), elevated levels of PLK1 inhibit PARP10 activity, which in turn, allows activation of the NF-κB pathway through NEMO." (PMID 40741921, 2025). "PLK1 is overexpressed in hepatocellular carcinoma (HCC), and inhibition of PLK1 activity can rapidly induce mitotic arrest and apoptosis in cancer cells." (PMID 36918935, 2023). "The PLKs have been implicated in a variety of cancers, such as hepatocellular carcinoma (HCC), with PLK1 typically overexpressed and PLKs 2–5 often downregulated." (PMID 24498222, 2014). "In human hepatocellular carcinoma (HCC), PLK1 acts as an oncogene and PLK2-4 presumably tumor suppressor genes." (PMID 25239093, 2014).
hepatocellular carcinoma (continued). "Nevertheless, UDCA inhibited the expression of cell cycle-related genes and the repression effect was enhanced with a time increase (PLK1, UBE2C, BUB1, CDC20, BIRC5, p <0.001) in hepatoma cell lines SNU387." (PMID 38255993, 2024). "Mechanistically, it was revealed that STK39 bound with PLK1 and then activated MAPK signaling pathway, which consequently promoted tumor proliferation and aggression in hepatocellular carcinoma." (PMID 37031178, 2023). "The three TSC2 null liver carcinoma cell lines SNU-886, SNU-878, and SNU-398 were uniformly sensitive to GSK461364, a PLK1 inhibitor, while in contrast the TSC1 null cell lines PEER and CAL-72 were not sensitive at all with IC50 values ranging from 5 to 33 nM." (PMID 33891611, 2021). "The expression of PLK1 is increased in many types of tumor, including cancer in brain, breast, colon, head and neck, lung, pancreas, bile duct, bladder, and prostate as well as hepatocellular carcinoma (HCC)." (PMID 25019081, 2014). "PLK1 interferes with TERT formation and inhibits the growth of hepatocellular carcinoma cells." (PMID 40486867, 2025). "Moreover, IGF2BP1 elevates the expression of Polo like kinase 1 (PLK1), thus inhibiting the apoptosis of hepatocellular carcinoma (HCC) cells." (PMID 37554271, 2023). "The results showed that AC099850.3 could promote the migration and proliferation of hepatocellular carcinoma cells in vitro, and RT-PCR experiments found that AC099850.3 could promote the expression of the cell cycle molecules BUB1, CDK1, PLK1, and TTK." (PMID 34123835, 2021).
gastric cancer (45 papers, 2004 to 2025). A primary or metastatic malignant neoplasm involving the stomach. "Plk1 is overexpressed in several types of human cancers such as lung, breast, and gastric cancer, suggesting that high Plk1 expression is associated with poor prognosis." (PMID 35300109, 2022). "Our study suggests that CCNA2 is a novel biomarker predictive of sensitivity to PLK1 inhibitors for the treatment of advanced gastric cancer, particularly cases carrying KRAS mutation." (PMID 32486290, 2020). "Inhibition of the SHCBP1 and PLK1 interaction sensitizes gastric cancer cells to trastuzumab treatment." (PMID 41009347, 2025). "Blocking the binding of SHCBP1 and PLK1 can enhance the sensitivity of gastric cancer cells to trastuzumab." (PMID 40799237, 2025). "BI 2536 is a highly selective and potent PLK 1 inhibitor that can regulate the malignant behavior of gastric cancer cells in combination with cisplatin." (PMID 38756785, 2024). "USP24 promotes tumor growth in gastric carcinoma by stabilizing PLK1 to activate NOTCH1 and increase aerobic glycolysis." (PMID 39605891, 2024). "Similar results were observed using the dual WEE1 and Polo-like kinase 1 (PLK1) inhibitor AZD1775 in gastric cancer cells, which disrupted HR repair and the DNA damage checkpoint, as well as sensitized HR-proficient cells to Olaparib." (PMID 35205643, 2022). "The PLK1/P13K/Akt pathway plays an important role in the development of gastric cancer and is inseparably related to ROS and RON." (PMID 36035159, 2022). "Recent studies have shown that PLK1 overexpression can promote the development of breast cancer, renal cell carcinoma, and gastric cancer." (PMID 35756492, 2022). "The PLK1-driven EMT has also been reported in gastric carcinoma cells, where the overexpression of PLK1 induced down-regulation of E-cadherin and up-regulation of N-cadherin, Slug and Twist, through the induction of PLK1-mediated AKT phosphorylation." (PMID 35719948, 2022). "The findings demonstrated that inhibiting BRD4 by ARV-825 led to an expression reduction in MYC and PLK1 at mRNA and protein levels in gastric cancer cells." (PMID 34733788, 2021). "Thousands of up- and downregulated genes were identified by RNA-seq analysis, among which MYC and PLK1 were confirmed as downregulated makers after treatment with ARV-825 in gastric cancer cells." (PMID 34733788, 2021). "Plk1 inhibition using siRNA or pharmacological inhibitors abrogates cancer cell invasion in various cancers like gastric cancer." (PMID 34646387, 2021). "ARV-825 induced degradation of BRD4, BRD2, BRD3, c-MYC, and polo-like kinase 1 (PLK1) proteins in four gastric cancer cell lines." (PMID 34733788, 2021). "PLK1 was also reported to promote Epithelial-Mesenchymal Transition (EMT), a biological process that was closely associated with cell stemness, in gastric carcinoma cells." (PMID 34266348, 2021). "Compared to resistant cells, gastric cancer cells sensitive to PLK1 inhibitors showed increased expression of cyclin A2." (PMID 32486290, 2020). "First, we sought to validate differential expression of cyclin A2 protein in gastric cancer cell lines selected from both sides of the drug response profile for PLK1 inhibitors." (PMID 32486290, 2020). "We performed pharmacogenomics analysis using a gastric cancer cell line panel and discovered a causal linkage cascade of oncogenic KRAS mutation, aberrant CCNA2 upregulation and hypersensitivity to PLK1 inhibitors." (PMID 32486290, 2020). "Further, we demonstrated that CCNA2 expression is elevated in KRAS mutant gastric cancer cell lines and primary tumors, resulting in an increased sensitivity to PLK1 inhibitors." (PMID 32486290, 2020). "In this study, SNPs rs2273535, rs1047972, rs911160 and rs8173 (AURKA), rs2241909 and rs2289590 (AURKB), rs758099 and rs11084490 (AURKC), and rs42873 (PLK1) mitotic kinases were screened for associations with the genetic susceptibility to gastric cancer (GC) in Bosnian population." (PMID 31521144, 2019).
gastric cancer (continued). "To increase our understanding of the clinical value and potential molecular mechanism of PLK1 in gastric cancer (GC), we performed this comprehensive investigation." (PMID 29190933, 2017). "It is possible that PLK1 inhibition will be of clinical utility in treating gastric cancer patients." (PMID 26576650, 2015). "For example, in gastric cancer, PLK1 drives EMT via AKT phosphorylation." (PMID 39451218, 2024). "Moreover, PLK1 is also highly expressed in certain kinds of cancer, such as esophageal cancer and gastric cancer." (PMID 34787756, 2022). "ARV-825 reduced MYC and PLK1 expression in gastric cancer cells." (PMID 34733788, 2021). "In this study, the authors demonstrate that HER2 promotes tumorigenesis in gastric cancer by regulating mitotic progression through a Shc1-SHCBP1-PLK1-MISP axis and they identify a compound, TFBG, able to disrupt SHCBP1/PLK1 interaction and to synergize with trastuzumab." (PMID 33990570, 2021). "The research work of Dang and other scholars proved that PLK1 may enhance the proliferation and migration of gastric cancer cells by participating in MEK-ERK pathway." (PMID 33354424, 2020). "We investigated the expression pattern of PLK1 in gastric cancer based on each independent dataset." (PMID 29190933, 2017). "Having established up-regulation of FOXM1 protein expression in gastric cancers, we next wanted to test whether we could detect co-upregulation of PLK1." (PMID 26576650, 2015). "PLK1 has separately been reported to be overexpressed in gastric cancer patients." (PMID 26576650, 2015). "PLK1 expression is upregulated in a number of tumors including esophageal carcinoma, multiple myeloma, gynecological malignant tumors, skin cancer, liver cancer, gastric carcinoma and cervical cancer." (PMID 23226764, 2012). "Poor prognosis in GC patients related with high expressions of cyclins.CCNA2 is a novel predictive biomarker of sensitivity to PLK1 inhibitors for the treatment of advanced gastric cancer, whose overexpression was an indicator of poor prognosis." (PMID 34126961, 2021). "Therefore, we hypothesized that aberrant upregulation of cyclin A2 in gastric cancer cells may elicit synthetic lethal vulnerability to PLK1 inhibition through failed cell cycle progression, particularly at the M phase." (PMID 32486290, 2020). "Therefore, we decided to further investigate whether CCNA2 may be a functional of differential responses to PLK1 inhibitors in gastric cancer." (PMID 32486290, 2020). "In addition, while depletion of mutant KRAS reversed cytotoxicity to BI-2536 and volasertib, co-expression of CCNA2 in this context was sufficient to reintroduce sensitivity, indicating that sensitivity to PLK1 inhibitors in KRAS mutant gastric cancer cells is mediated by CCNA2 upregulation." (PMID 32486290, 2020). "In gastric cancer, SHCBP1 interacts with PLK1 to enhance MISP phosphorylation, regulating trastuzumab sensitivity." (PMID 40799237, 2025). "In gastric cancer, after stimulation by EGF, SHCBP1 is translocated into the nucleus and binds to PLK1 to promote the phosphorylation of MISP." (PMID 40799237, 2025). "PLK1 is proposed as an important driver in EMT and metastasis 18 in gastric cancer 19, lung cancer 20, pancreatic cancer 21, and kidney cancer." (PMID 36793862, 2023). "Previous studies have reported the differential expression of the genes we identified in gastric cancer, but few studies have reported the differential expression of AURKB, CCNA2, PLK1, TPX2, and CDK1 in gastric cancer." (PMID 37238607, 2023). "Studies had shown that the upregulated expression of PLK1 can activate the PI3K/AKT signaling pathway, promote the proliferation of gastric mucosal epithelial cells, and increase the possibility of gastric cancer." (PMID 35756492, 2022). "With regard to the co-expression network of stemness-related genes, PLK1 promotes EMT and metastasis in gastric carcinoma." (PMID 34178686, 2021).
gastric cancer (continued). "FOXM1 is overexpressed in a large proportion of gastric carcinomas at the protein level and FOXM1 and PLK1 are concomitantly overexpressed at the mRNA level in this cancer type." (PMID 26576650, 2015). "Furthermore, inhibition of PLK1 by inhibitor BI2536 enhanced the CDDP sensitivity of oesophageal squamous cell carcinoma and gastric cancer cells." (PMID 35910374, 2022). "ARV-825, a BRD4 inhibitor, could effectively suppress the growth and elevate the apoptosis of gastric cancer cells via transcription downregulation of c-MYC and PLK1." (PMID 34733788, 2021). "We consider this an important finding as PLK1 silencing is already part of an integrated oncolytic adenovirus approach currently being studied in mice models of orthotopic gastric carcinoma and has promise due to the lack of a reported measurable immune response of siRNA-based therapeutics." (PMID 20805891, 2010). "Plk1 was independent of HIF-1α and HIF-2α in stomach cancer, uterine cancer, and uveal melanoma." (PMID 33547392, 2021).
bladder cancer (43 papers, 2009 to 2025). "rs40076 is located in the intronic region of PLK1, affects mRNA splicing or transcriptional regulation, and can be used as a predictor of bladder cancer susceptibility and survival." (PMID 40612941, 2025). "PLK-1 expression is upregulated in a variety of cancer types, including bladder cancer, and its overexpression is linked to poor prognosis, relapse, and metastasis." (PMID 39355533, 2024). "As overexpression of polo-like kinase (PLK)-1 is associated with the development of bladder cancer, one study showed that treatment with PLK-1 siRNA containing exosomes inhibited bladder cancer growth." (PMID 33028046, 2020). "In previous experiments, we revealed that PLK1 is upregulated in bladder cancer tissues and is thus associated with malignancy." (PMID 29246203, 2017). "Five downstream genes of PLK1 were associated with the regulation of cell proliferation, invasion and migration in bladder cancer." (PMID 29246203, 2017). "We selected four candidate SNPs for further investigation, which were either located within the regulatory regions of PLK1 (rs57973275, rs16972787 and rs27770) or showed an association with bladder cancer outcome in a previous study (rs40076)." (PMID 24767679, 2014). "As part of a polymorphism panel, another polymorphism located within intron 3 of PLK1 (rs40076) has been suggested as an outcome predictor for Caucasian bladder cancer patients." (PMID 24767679, 2014). "Furthermore, the strong linkage disequilibrium suggests rs27770 as the underlying functional SNP in the detected association of the PLK1 intron 3 SNP rs40076 with bladder cancer outcome." (PMID 24767679, 2014). "The authors showed that the PLK-1 siRNA-loaded mesenchymal stem cell-derived exosomes induced knockdown of PLK-1 mRNA and protein expression, induced apoptosis, and inhibited bladder cancer cell proliferation." (PMID 39355533, 2024). "Several studies have demonstrated that the knockdown of PLK-1 induces cell cycle arrest and apoptosis in bladder cancer cells." (PMID 39355533, 2024). "In one study, exosomes were isolated from HEK293 and mesenchymal stem cells by ultracentrifugation and used to deliver PLK-1 siRNA to bladder cancer cells." (PMID 39355533, 2024). "siR-PLK-1-carrying EV delivery to bladder cancer cells resulted in the suppression of PLK-1 and contributed to cell cycle arrest and apoptosis." (PMID 37189850, 2023). "MSC exosomes are effectively used as a delivery vector to transport PLK-1 siRNA to bladder cancer cells in vitro, resulting in selective gene silencing of PLK-1." (PMID 36824409, 2023). "PLK1-siRNA was introduced into exosomes by electroporation, and exposure of bladder cancer cells to these exosomes resulted in a significant decrease in PLK1 mRNA levels and subsequent cancer eradication." (PMID 35765040, 2022). "MSC-derived exosomes were genetically engineered by loading them with polo-like kinase 1 (PLK-1)-siRNA and were utilized for PLK1 gene silencing in bladder cancer." (PMID 33477340, 2021). "Other groups have attempted exosomal silencing by siRNA with similar results; i.e., exosomal delivery of a PLK-1 gene-specific siRNA silencer in UMUC3 bladder cancer cell lines showed >60% silencing of PLK-1 expression." (PMID 32932883, 2020). "HEK293 and MSC exosomes were therefore effectively used as delivery vectors to transport PLK-1 small interfering RNA (siRNA) to bladder cancer cells in vitro, resulting in the selective gene silencing of PLK1." (PMID 33396739, 2020). "The exosomes that are derived from MSC and HEK293 were used to deliver siRNA that target PKL-1 in bladder cancer cells and showed the reduced expression of polo-like kinase 1 (PLK-1)." (PMID 30940145, 2019). "Here, we aimed to determine the downstream genes of PLK1 and their effects on the carcinogenesis and progression of bladder cancer." (PMID 29246203, 2017).